FOXR1 (forkhead box R1)
Description:
Transcription factor which acts as both an activator and a repressor. Activates transcription of a number of genes including the heat shock chaperones HSPA1A and HSPA6 and the antioxidant NADPH-dependent reductase DHRS2 which are involved in protection against oxidative stress. Required for normal brain development (By similarity).
Synonyms: FOXN5; DLNB13
Tractability: No criterion of Open Targets' tractability assessment is met for any kind of drug.
Gene: Protein-coding gene on chromosome 11 (118,971,712 to 118,981,287, forward strand). Ensembl gene ENSG00000176302.
Subcellular location: Nucleus; Cytoplasm; Cytoplasm, perinuclear region
Subcellular location (Human Protein Atlas): Nucleoplasm; Cytosol
Gene Ontology:
Molecular function: DNA-binding transcription activator activity, RNA polymerase II-specific; DNA-binding transcription repressor activity, RNA polymerase II-specific; protein binding; DNA-binding transcription factor activity, RNA polymerase II-specific; sequence-specific double-stranded DNA binding; DNA-binding transcription factor activity; sequence-specific DNA binding
Biological process: positive regulation of transcription by RNA polymerase II; regulation of transcription by RNA polymerase II; brain development; negative regulation of transcription by RNA polymerase II; regulation of DNA-templated transcription
Cellular component: cytoplasm; nucleus; chromatin; perinuclear region of cytoplasm
Genetic constraint (gnomAD): Loss-of-function variants: 25 observed, 35.47 expected, observed/expected ratio (o/e) 0.7, 90% interval 0.51 to 0.98. The upper end of that interval is the gene's LOEUF score, 0.98, which puts it in group 4 of 6, group 1 being the genes least tolerant of losing a copy. Missense variants: 373 observed, 376.55 expected, observed/expected ratio (o/e) 0.99, 90% interval 0.91 to 1.08. Synonymous variants: 153 observed, 140.51 expected, observed/expected ratio (o/e) 1.09, 90% interval 0.95 to 1.25.
Homologues: Orthologues: chimpanzee FOXR1 (99% identical), macaque FOXR1 (97% identical), pig FOXR1 (85% identical), dog FOXR1 (84% identical), rat Foxr1 (69% identical), mouse Foxr1 (42% identical). Paralogues in human: FOXR2 (57% identical), FOXN1 (22% identical), FOXA2 (18% identical), FOXC1 (17% identical), FOXE1 (17% identical), FOXK2 (17% identical), FOXD1 (17% identical), FOXE3 (17% identical), FOXO1 (17% identical), FOXF1 (16% identical), FOXD2 (16% identical), FOXD4 (16% identical), and 29 more.
Diseases named in the same sentence as FOXR1 in open-access papers:
FOXR1 is named in the same sentence as 19 diseases in open-access papers, as found by Europe PMC text mining. Sharing a sentence is not in itself a finding about the gene and the disease. The quoted sentences say what the papers report.
microcephaly (3 papers, 2021 to 2025). A congenital or acquired developmental disorder in which the circumference of the head is smaller than normal for the person's age and sex. "Despite this constraint, our analysis of surviving knockout mice reveals that Foxr1 loss results in microcephaly characterized by cortical thinning and hippocampal hypoplasia at birth." (PMID 40497137, 2025). "Despite this limitation, our findings demonstrate that in the subset of Foxr1 knockouts that survive to birth, loss of Foxr1 leads to microcephaly, primarily driven by cortical reduction." (PMID 40497137, 2025). "Recently, a single de novo missense variant in FOXR1 (M280L) in an individual with severe neurological symptoms, including postnatal microcephaly, progressive brain atrophy, and global developmental delay, has been reported." (PMID 38094004, 2023). "Exome sequencing of an individual with severe neurological symptoms including postnatal microcephaly, progressive brain atrophy, and global developmental delay implicated a de novo missense variant in the FOXR1 gene as potentially causative." (PMID 34723967, 2021). "We report an individual with severe neurological symptoms including postnatal microcephaly, progressive brain atrophy and global developmental delay associated with a de novo missense variant (M280L) in the FOXR1 gene." (PMID 34723967, 2021). "These region- and layer-specific effects underscore the essential role of Foxr1 in brain development and have broader implications for understanding the molecular underpinnings of microcephaly and related neurodevelopmental disorders." (PMID 40497137, 2025). "Here, we extend these findings by showing that Foxr1 knockout mice develop microcephaly accompanied by cortical and hippocampal hypoplasia at postnatal day 0 (P0)." (PMID 40497137, 2025). "Foxr1 knockout mice exhibit microcephaly characterized by cortical thinning and hippocampal hypoplasia." (PMID 40497137, 2025). "Here, we demonstrate Foxr1 deletion results in microcephaly, cortical thinning, and hippocampal hypoplasia." (PMID 40497137, 2025). "Because the microcephaly in Foxr1 knockout mice is primarily driven by cortical reduction, we next examined whether this was associated with layer-specific defects in the cortex at P0." (PMID 40497137, 2025). "The phenotypes described in this individual are consistent with those detected in Foxr1 knockout mice, suggesting that FOXR1 would be a responsible gene for the observed phenotypes, including microcephaly; however, validation in additional cases is warranted before drawing definitive conclusions." (PMID 38094004, 2023). "Supporting the potential significance of FOXR1 in the brain, the NIH Undiagnosed Disease Network identified an individual with a heterozygous FOXR1 variant presenting severe neurological symptoms including postnatal microcephaly, progressive brain atrophy, and global developmental delay." (PMID 40497137, 2025). "Interestingly, some of the upregulated genes by FOXR1 overexpression are involved in ribosome biogenesis (e.g., ribosome biogenesis regulator 1 and RRS1), an essential driver in neurodevelopment, whose dysregulation is associated with microcephaly and other neurodevelopmental syndromes." (PMID 38094004, 2023).
B-cell lymphoma (2 papers, 2022 to 2024). "Interestingly, some of these genes, such as LEP, ALOX12, RARRES2, DLEU7, and FOXR1, have been reported to be associated with other hematologic malignancies, including AML, chronic lymphocytic leukemia (CLL), and B-cell lymphoma." (PMID 35847864, 2022). "The FOXR1 gene and KMT2A in the 11q23 segment are related to the occurrence of B-cell lymphoma." (PMID 38172714, 2024).
meningioma (1 paper, 2013). A generally slow growing tumor attached to the dura mater. "For the malignant meningiomas in our study, 26 genes were identified as significantly hypermethylated at promoter CpG islands, including eight genes involved in the biological pathway of neurogenesis (BARHL2, TLX3, FOXR1, HOXA11, HOXA6, HOXA9, OTX2 and PAX3)." (PMID 23349797, 2013).
metastatic prostate carcinoma (1 paper, 2022). A carcinoma that arises from the prostate gland and has spread to other anatomic sites. "Almost all of the FOX genes were differentially expressed in prostate cancer, prostate carcinoma, and metastatic prostate cancer, except FOXA3, FOXB2, FOXC2, FOXI2, FOXI3, FOXP4, and FOXR1." (PMID 36292640, 2022).
neuroblastoma (1 paper, 2019). Neuroblastoma (NB) is the most common solid, extracranial childhood tumor. "FOXN5 (FOXR1) was originally reported as a candidate tumor suppressor gene, with mutations leading to abnormal structural changes closely associated with the occurrence of neuroblastoma." (PMID 31214487, 2019).
neuroepithelial tumor (1 paper, 2020). "Next, CNS high-grade neuroepithelial tumor with genetic alterations in either BCOR (HGNET-BCOR), FOXR1 (HGNET-FOXR1) or MN1 (HGNET-MN1) are newly described subtypes all characterized by distinct molecular alterations." (PMID 33260839, 2020).
tumor (4 papers, 2016 to 2023). "FOXA1, FOXM1, FOXO subfamily genes, and FOXR1 have been widely studied and confirmed to promote tumor progression through various pathways, such as proliferation, invasion, and immunity." (PMID 37563111, 2023).
cancer (3 papers, 2021 to 2022). A tumor composed of atypical neoplastic, often pleomorphic cells that invade other tissues. "In addition, several point mutations within human FOXR1 have been shown to be associated with a variety of carcinomas, although functional characterization of these oncogenic FOXR1 mutants has not been performed." (PMID 34723967, 2021).
neurodevelopmental disorder (2 papers, 2021 to 2025). A behavioral and cognitive disorder with onset during the developmental period that involves impaired or aberrant development of intellectual, motor, or social functions. "The UDN has identified an individual presenting with severe neurological symptoms and linked a missense variant in the FOXR1 gene as a potential variant underlying the genetic etiology of the rare neurodevelopmental disorder." (PMID 34723967, 2021). "Here, we report a human neurodevelopmental disorder associated with a rare variant in FOXR1." (PMID 34723967, 2021).
FOXR1 also shares sentences with these, for which no sentence is quoted: Brain atrophy (2 papers); developmental delay (2); infection (2); brain cancer (1); brain tumor (1); chronic lymphocytic leukemia (1); Crohn disease (1); glioma (1); hematologic malignancies (1); prostate carcinoma (1).